RNU6-249P (RNA, U6 small nuclear 249, pseudogene)
Gene: Small nuclear RNA gene on chromosome 12 (42,398,550 to 42,398,651, forward strand). Ensembl gene ENSG00000199886.
Homologues: Orthologues: chimpanzee U6 (97% identical), macaque U6 (92% identical), guinea pig U6 (85% identical), rabbit U6 (85% identical), guinea pig U6 (80% identical), dog U6 (77% identical), mouse Gm24646 (77% identical), pig U6 (72% identical), mouse Gm24905 (71% identical). Paralogues in human: RNU6-560P (91% identical), RNU6-28P (89% identical), RNU6-11P (88% identical), RNU6-37P (88% identical), RNU6-86P (88% identical), RNU6-1036P (87% identical), RNU6-128P (87% identical), RNU6-1310P (87% identical), RNU6-34P (87% identical), RNU6-38P (87% identical), RNU6-46P (87% identical), RNU6-1 (86% identical), and 1290 more.